LYZ (lysozyme)
Diseases named in the same sentence as LYZ in open-access papers (continued):
Sharing a sentence is not in itself a finding about the gene and the disease.
infection (continued). "It is a leucocytic-derived mucolytic enzyme, so the lysozyme is greatly elevated than normal against severe infection with EMC42,43." (PMID 37482562, 2023). "24h post-infection, lysozyme activity decreased in most cases, but remained at similar levels as those observed 4h post-infection in the hemolymph of insects injected with Enterobacter sp." (PMID 36689436, 2023). "During co- or single infection with E. ictaluri, an upregulation of lysozyme activity and pro-inflammatory cytokines was observed." (PMID 36986384, 2023). "The expression of the antimicrobial compounds (c3, mpo, and lysozyme) mRNA showed a similar pattern, meaning a delayed answer after 24 h post-infection and then a return to the control state except for the mpo." (PMID 36838503, 2023). "This is in agreement with previous work demonstrating that several bacterial species transition to L-forms within macrophages (eg, in response to lysozyme) and during zebrafish infection." (PMID 37556724, 2023). "We found that inflammatory chemokines and the antibacterial enzyme lysozyme were increased in scarring, while IL-8 was increased during infection." (PMID 37862368, 2023). "Cryptdin and lysozyme are the two AMPs for which mRNA expression was reduced after infection suggesting an escape mechanism induced by the bacteria." (PMID 35733975, 2022). "According to two-way ANOVA, lysozyme activity was significantly affected by P. locustae concentration(F9,150 = 4,294; P < 0.001), duration of infection (F2,150 = 323.3; P < 0.001), and their interaction (F18,150 = 272; P < 0.001)." (PMID 35935997, 2022). "This research discovered a link between dietary SeE-SP and lysozyme activity, which led to increased disease resistance against infections." (PMID 36009291, 2022). "Gene expression profiling of penaeidin and lysozyme was performed to support the findings of infection assays of the current study." (PMID 35056639, 2022). "The simultaneous increase in the percentage of cells with SWC3a and CD11+ expression, as well as in the concentration of lysozyme and acute phase proteins, indicates intensification of phagocytosis, which protects the body against infection." (PMID 34596883, 2022). "We have observed that C. elegans can produce a variety of antibacterial substances through the DAF-16 pathway to defend against BMB171/Cry5Ba infection, such as lysozyme and thaumatin." (PMID 35773333, 2022). "The results showed that 100 and 150 mg/kg GABA supplementation consistently yielded significant improvements (p < 0.05) in growth, intestinal amylase, serum lysozyme, and survival against infection with Streptococcus iniae." (PMID 35158571, 2022). "We found that the lysozyme activity and hepcidin and NK-lysin levels in the serum were unmodified upon infection." (PMID 35055122, 2022). "While the induction of AMPs and lysozyme during fungal entomopathogenic infections have been reported, their contribution to the mosquito antifungal response has not been evaluated." (PMID 36687607, 2022). "This was explained to be due to the fact that putrescine and cadaverine, as by-products of amino acid degradation through bacterial infection, provide the foul smell, which can then act as an activation signal for lysozyme to help clear up the infection site." (PMID 35392564, 2022). "An anti-bacterial enzyme such as lysozyme (LYZ) responds against the infection of Vibrio harveyi, V. campbellii, V. penaecida, V. parahaemolyticus, and white spot syndrome virus (WSSV)." (PMID 36496829, 2022). "In another mouse model of infection with FvB mice (susceptible model), STm was shown to increase the number of paneth cells but inhibit Cryptdin (α-defensin) and lysozyme expression as soon as 1 day after infection by a mechanism involving T3SS-1." (PMID 35733975, 2022). "In this study, we assessed the induction of Ae. aegypti AMPs and lysozyme genes at two points of infection and against distinct entomopathogenic fungi." (PMID 36687607, 2022).
infection (continued). "Lysozyme is an enzyme of the innate immune response that acts as the main effector molecule in anti-bacterial and anti-inflammatory activities during infection." (PMID 36138767, 2022). "The non-specific immunity of fish mainly products in the blood and mucous membranes, including different types of cells (leukocytes and macrophages) and their products (complement, lysozyme, superoxide dismutase, etc.), which can resist pathogen infection." (PMID 35698139, 2022). "In this study, significantly high expression of C-type lysozyme was noticed in the systemic and mucosal tissues of BI-vaccinated hosts after infection with S. iniae and A. hydrophila, respectively." (PMID 36138746, 2022). "Considering possible biotechnological applications, antimicrobials with the capacity to mitigate the infection by CLas that are innocuous for humans were considered; namely, human β-defensin and lysozyme." (PMID 35178061, 2022). "In this experiment, compared with the control group, the activity of lysozyme in the serum of grass carp was higher at before and after infection." (PMID 36591242, 2022). "In the case of eye diseases, the amount of lysozyme in the tear fluid is reduced, making the eye vulnerable to infection by micro-organisms." (PMID 36139845, 2022). "Fish live in an aqueous environment that is rich in pathogens, and lysozyme is critical in the defense against infection." (PMID 35873430, 2022). "Direct inhibition of infection by an attack of pathogens occurs with Lf and CM lysozyme, which enhances the local Th1 response." (PMID 35493477, 2022). "In Spodoptera exigua, lysozyme and other antibacterial active substances are inhibited in the later stage of infection." (PMID 35935997, 2022). "In particular, the up-regulation of lysozyme activity in Cihep -3d group and Cihep+CS-3d group was the most obvious after infection." (PMID 36591242, 2022). "Expression of the lysozyme gene in R. philippinarum was significantly upregulated after V. anguillarum infection, peaking at 48 h after infection, and then decreasing by 72 h, although the overall expression remained higher than that in the control group." (PMID 35615362, 2022). "strains; these enzymes include a peptidoglycan-N-acetylglucosamine deacetylase, which plays a role in peptidoglycan deacetylation, avoiding eukaryotic lysozyme recognition during infection." (PMID 36142880, 2022). "An alternative approach to treat the infection by E. amylovora using a combination of lysozyme and of a synthetic peptide derivative was described in a paper published in 2017." (PMID 34943746, 2021). "Lysozyme and hGIIA are both secreted by epithelial cells and immune cells that are recruited towards the site of infection." (PMID 33481964, 2021). "The observation of prophages in the snail endosymbionts and expression of the phage integrase gene suggested the presence of lysogenic infection, and the expression of phage structural protein and lysozyme genes indicated active lytic infection." (PMID 34479645, 2021). "The infection of vAh significantly induced transcription of apolipoprotein A1, chicken-type lysozyme, G-protein coupled receptor 18, and goose-type lysozyme in kidney, liver, and other tissues of channel catfish." (PMID 34827972, 2021). "In cell-free hemolymph from naïve larvae, we measured a basal activity of lysozyme (2288 ± 211 U/ml), which progressively increased after infection with the bacterial mix." (PMID 34867970, 2021). "Among the five innate immune genes, the elevated il1β, il8, and lysozyme were overlapped in the vaccine-immunized zebrafish and the survival from the infection." (PMID 34950133, 2021). "The high number of leukocytes and a large amount of lysozyme in the treatment using PAPS which is similar to an infection by a pathogen indicated the success of PAPS in triggering the fish’s immune system when developing an immune response." (PMID 37767359, 2021).
infection (continued). "In a 2017 publication, a smart antimicrobial system, activated in the case of infection, based on elevated lysozyme activity, was presented." (PMID 34943746, 2021). "Our study found several immune-related DETs that are up-regulated in virus-exposed guts, including apolipophorins, lysozyme, and trypsin, but only during the early stage (3-L1) of the infection." (PMID 34758725, 2021). "Over the course of bacterial infection, there is usually an increase in lysozyme activity, which was noted, among others, over the course of infection with A. punctata, A. salmonicida, or E. tarda." (PMID 34359116, 2021). "Genes encoding C3, cathelicidins, lysozyme, SAA, IgM and IL-17C1 were significantly up-regulated at this late infection time-point." (PMID 34497310, 2021). "The test showed that lysozyme strongly synergized with AS-48 in in vitro cultures, whereas no synergistic effect was observed in the intracellular model of infections." (PMID 34943746, 2021). "Among the five innate immune genes, the elevated il1β, il8, and lysozyme are overlapped in the vaccine-immunized zebrafish and the survival from the infection." (PMID 34950133, 2021). "Insects can prevent infection by synthesizing antibacterial proteins such as cecropin, insect defensin, large glycine-rich protein, small proline-rich protein, and lysozyme." (PMID 33726671, 2021). "Through mechanisms such as blocking of phage DNA entry into the lysogen’s cytoplasm or inhibition of phage lysozyme, the superinfection immunity resists secondary infection by the same or closely related phages, providing the lysogen with a survival advantage." (PMID 33920555, 2021). "Infection with the IPNV has been shown to reduce lysozyme activity, which has a bactericidal effect." (PMID 34359116, 2021). "In bivalves subjected to infection, lysozyme has been shown to primarily increase expression in mucosal tissues such as the mantle, gills, and digestive gland." (PMID 33500457, 2021). "N-deacetylation of GlcNAc, for example, occurs in pathogens including various streptococci and Listeria monocytogenes, prevents PG hydrolysis by lysozyme, and helps cells to evade the immune response during infection." (PMID 34721369, 2021). "Lysozyme, C3 and C4 play pivotal roles in innate immunity and protect animals from pathological infection." (PMID 34573080, 2021). "During the infection of bacterial pathogens, lysozyme can reduce the pathogen-induced inflammation by inhibiting the growth of the bacteria." (PMID 34946706, 2021). "The increased lysozyme activity refers to the ability of fish to hydrolysis the cell walls of harmful bacteria, while phagocytosis is a cellular immune defense against infection." (PMID 34359255, 2021). "Emerging researches show evidence that lysozyme can not only directly resist bacteria, but also regulate the host immune response to infection." (PMID 34925025, 2021). "In contrast to lysozyme, the transcription of both AMPs was highly stimulated by infection both in the fat body and in hemocytes." (PMID 34867970, 2021). "The number of lysozyme + cells increased slightly after Nc-Spain7 infection (P < 0.05), and iNOS + staining was found in trophoblast cells infected by both isolates." (PMID 32552750, 2020). "The T4 Spackle protein (encoded by gene 61.3) has been thought to play a role in the inhibition of gp5 lysozyme activity and, as a consequence, in making cells infected by bacteriophage T4 resistant to later infection by T4 and closely related phages." (PMID 32987925, 2020). "After infection by E. ictaluri, the lysozyme and complement activities as well as the total Ig mostly decreased but were still significantly higher in some extract-based diets compared to those of the control." (PMID 32431710, 2020).
infection (continued). "Interestingly, infection with invasive bacteria causes PCs to switch to secretory autophagy, an autophagy-based alternative secretory pathway that is characterized by diffuse lysozyme expression, hence resembling the dysfunctional PC phenotype observed during injury and inflammation." (PMID 33469536, 2020). "Consistent with the results from RNA sequencing, infection induced expression of antimicrobial proteins (nlp-30, nlp-34 and spp-1) and lysozyme (ilys-2) was severely compromised by rnp-6 G281D substitution." (PMID 32538777, 2020). "In this study, vaccinated tilapia showed a significant increase of lysozyme activity compared to the unvaccinated fish in both pre- and post-infection." (PMID 32615969, 2020). "At the site of infection, lysozyme binds to the fungal cell surface (i.e. membrane or cell wall) and will cause osmotic imbalance and cell death as reported in C. albicans." (PMID 32267851, 2020). "After 24 h of infection, increased serum (lysozyme) and skin barrier functions, down-regulation of interleukin-1beta, and upregulation of interleukin-10 were found in HI-supplemented-PBM-fed fish." (PMID 33521040, 2020). "strains; these included O-acetylase (OafA) and Peptidoglycan-N-acetylglucosamine deacetylase, which play a role in peptidoglycan deacetylation, avoiding eukaryotic lysozyme recognition during infection." (PMID 32512932, 2020). "Some genes have been found to be upregulated only at the late phase of infection such as macroglobulin/complement, serine protease inhibitor, C-type lysozyme (LYSC11) and the 40S ribosomal protein S2 (RpS2)." (PMID 32758286, 2020). "In this study, supplementation with GOS increased the mRNA level of interferon and lysozyme, which are involved in fighting infection." (PMID 32150980, 2020). "There is evidence for upregulated lysozyme gene expression during infection in insects (e.g. Manduca sexta; Trichoplusia ni)." (PMID 31091239, 2019). "Many pathogens have developed a mechanism to render lysozyme ineffective, thus increasing their pathogenicity as well as the severity of infection." (PMID 31323733, 2019). "Nisin and lysozyme were effective at later steps of infection than lactoferrin, and the intensity of their influence did not decrease with time." (PMID 31488163, 2019). "For example, the expression of two cecropin genes is increased at 6 h post infection and that of two defensin and two lysozyme genes is decreased at 12 h post infection." (PMID 30813894, 2019). "Lysozyme reduced the viral yield only when present in the culture medium throughout the entire duration of infection (adsorption+post-adsorption)." (PMID 31488163, 2019). "After 12 h of infection, the expression levels of gallerimycin, galiomycin, and lysozyme were significantly higher in larvae infected with the lpxO mutant than in larvae infected with the wild-type strain." (PMID 30745327, 2019). "We observed in this study that, even before infection, the groups that were fed the products had higher lysozyme activity in comparison to the NC group, although this difference was not significant." (PMID 30988331, 2019). "Many factors, such as stress and infection, sexual maturity, nutrition, toxic substances, and others, have been studied in relation to the activity levels of lysozyme in fish." (PMID 31244883, 2019). "supplementation nutritionally-modulated fish resistance to infection, by accessing the innate immune indicators lysozyme and peroxidase." (PMID 31695116, 2019). "The elevated lysozyme expression, at the recovery from infection stage in the WT-supplemented fish, was in line with the elevated expression of the COX-2 gene, which is generally associated with a pro-inflammatory effect." (PMID 30237797, 2018). "Collagen is exposed by an infection of the endocardium due to damaged endothelium and activated macrophages secrete lysozyme." (PMID 29373594, 2018).
infection (continued). "The greatest challenge encountered by ExPEC during an infection is posed by the host defense mechanisms, including lysozyme." (PMID 29405825, 2018). "Predominantly composed of water and mucins, CVM also contains high levels of immuno-active proteins such as immunoglobulin A (IgA), lactoferrin and lysozyme which protect against infection by blocking adhesion and mediating microbial killing." (PMID 30117040, 2018). "This has been shown in an animal infection model as well as in macrophages, where lysozyme activity from the host converts walled bacteria into CWD cells." (PMID 30514921, 2018). "Bacterial proteinaceous lysozyme inhibitors protect the cell wall against host lysozyme attack during infection." (PMID 30564232, 2018). "To test the basis for the attenuation of ΔsliC bacteria relative to wild type, we next conducted competitive infections in mice that were genetically defective for lysozyme using C57BL/6J mice as the background controls." (PMID 29975784, 2018). "Supporting these findings, gonococci lacking NGO1063 show comparable fitness to wild type bacteria during competitive infection in lysozyme-defective mice, but are attenuated in wild-type mice of the same background." (PMID 29975784, 2018). "At 8 h post infection, the macrophages were treated with lysis buffer (Promega, Madison, WI) containing 5 mg/mL lysozyme." (PMID 29930310, 2018). "Total lysozyme level is a tool to measure the humoral component of the non-specific defence mechanism (innate immunity), which can be used to detect infections or injections of foreign material, including bacteria." (PMID 30984371, 2018). "The effect of BP100 applied preventively, alone or combined with lysozyme, on the inhibition of infections of E. amylovora in pear leaves was determined in four assays." (PMID 28212623, 2017). "Infection with the 52145‐ΔpmrC‐ΔlpxO‐ΔmgrB, 52145‐ΔmgrB‐ΔlpxO‐ΔpmrF and 52145‐ΔpmrC‐ΔlpxO‐ΔmgrB‐ΔpmrF triple and quadruple mutants restored lysozyme expression to wild‐type levels." (PMID 28202493, 2017). "Because pgdA mutants in these species also display decreased survival in vivo, it implies that there are membrane-disrupting conditions that increase sensitivity to lysozyme during infection." (PMID 28934357, 2017). "Based on these findings, we posit a model where lysozyme activities must be balanced temporally and spatially to appropriately tune immune responses during the course of infection." (PMID 28934357, 2017). "The triple β-helix is reminiscent of the long β-helix in gp5 (gp5 is the tail lysozyme of phage T4, which functions as a cell-puncturing device during infection)." (PMID 28665339, 2017). "Together, these results suggest that human lysozyme is ineffective in killing P. aeruginosa during infection." (PMID 28299285, 2017). "If these activities of lysozyme occur later in the course of infection, they are likely to be important for the resolution of infection." (PMID 28934357, 2017). "Such defective mutants were found to be incapable of propagating in airway mucus secretions (AMSs) or establishing infection in the mouse airway, two locations where lysozyme is present in high concentrations." (PMID 28299285, 2017). "Several prophenoloxidase and 1 c-type lysozyme upregulated intermittently throughout the infection stages." (PMID 28871168, 2017). "After 8 h of infection, the expression of lysozyme, gallerimycin and galiomycin was significantly (P < 0.0001) lower in 52145‐ΔmgrB‐infected larvae than in the wild‐type‐infected larvae." (PMID 28202493, 2017). "Lysozyme (LYSO) is an enzyme that is upregulated in many organisms during the innate immune response against infection by bacterial pathogens." (PMID 28184027, 2017). "One intriguing conundrum that still remains to be resolved is the dual, potentially contradictory role of lysozyme in the immune response to infection." (PMID 28934357, 2017).